IL1B (interleukin 1 beta)
Diseases named in the same sentence as IL1B in open-access papers (continued):
Sharing a sentence is not in itself a finding about the gene and the disease.
acute coronary syndrome (29 papers, 2012 to 2025). Signs and symptoms related to acute ischemia of the myocardium secondary to coronary artery disease. "One study that investigated IL-1B −511 C/T polymorphism initially showed a correlation between suicidal ideation in acute coronary-syndrome patients." (PMID 40282388, 2025). "In a previous study, IL-1β levels were associated with a less favorable prognosis after acute coronary syndrome." (PMID 29051757, 2017). "Cox proportional hazard ratios (HR) with 95% confidence interval in brackets for the association between haplotypes of single nucleotide polymorphisms in IL1B and incident acute coronary syndrome." (PMID 22768033, 2012). "Cox proportional hazard ratios (HR) with 95% confidence interval in brackets for the association between single nucleotide polymorphisms in IL1B and incident acute coronary syndrome." (PMID 22768033, 2012). "There is clinical evidence supporting the prognostic value of CRP and IL-6 in acute coronary syndrome; however, the relevance of IL-1β and TNF-α as prognostic markers in this context remains uncertain." (PMID 40168324, 2025). "Specifically, elevated concentrations of proinflammatory cytokines, such as interleukin-1 beta (IL-1β), tumor necrosis factor-alpha (TNF-α), and interferon-gamma (IFN-γ), are associated with the increased risks of acute coronary syndrome." (PMID 39201047, 2024). "Infarcted cardiomyocytes cause the release of IL-1α, epithelial injury stimulates the release of IL-1β, while monocytes are a source of IL-1β in acute coronary syndromes." (PMID 35888173, 2022). "Deepening to the mechanism, monocyte-derived EVs carrying IL-1β are involved in EC activation and, consistently, IL-1β-rich eEVs in inflammation in the setting of acute coronary syndrome (ACS)." (PMID 35681540, 2022). "It has been found that patients with acute coronary syndrome have the highest transcoronary numbers of IL-1β, IL-6, and IL-18 compared to those with chronic coronary syndromes." (PMID 32550081, 2020). "In patients with acute coronary syndrome, the monocytes exhibited a reduction in secreted levels of IL-1β after they received a low dose of colchicine." (PMID 32550081, 2020). "The recent results of the Canakinumab Antiinflammatory Thrombosis Outcome Study (CANTOS) strengthen the potential implication of IL-1β in conditioning the clinical course of patients after an acute coronary syndrome (ACS)." (PMID 32116755, 2020). "Notably, selective IL-1β blockade reduced major adverse cardiovascular events in patients post-acute coronary syndrome in the CANTOS trial at the expense of slightly more serious infections." (PMID 40956333, 2025). "Moreover, colchicine administration contributed to the reduction in IL-1β, IL-18, and IL-6 in patients with acute coronary syndrome." (PMID 34440608, 2021). "In support, post-acute coronary syndrome patients with CKD were observed to have a larger absolute risk reductions following IL-1β antibody compared with non-CKD patients." (PMID 33602971, 2021). "There are several studies on the relationship between the expression of TNF-α and IL-1β with secondary ventricular arrhythmias in patients with acute coronary syndromes, in which TNF-α and IL-1β are significantly upregulated and the levels increase with the deterioration of ventricular arrhythmia." (PMID 29744364, 2018). "In addition, IL-1B is considered to be the central link in acute coronary syndrome, and it may be closely related to the occurrence of cardiovascular disease in the later stages of SS." (PMID 38728503, 2024). "Consequently, TNF-α and IL-1β are helpful in predicting the occurrence of secondary ventricular arrhythmia in patients with acute coronary syndrome and could be applied as useful biomarkers in estimating the severity of ventricular arrhythmia." (PMID 29744364, 2018).
acute coronary syndrome (continued). "However, the prospective associations between functional single nucleotide polymorphisms (SNPs) in IL1B and incident acute coronary syndrome (ACS) have not been thoroughly investigated." (PMID 22768033, 2012). "Thus, IL1B expression by itself may influence the inflammatory processes in the arterial wall that lead to the development of atherosclerotic plaques and acute coronary syndrome(ACS)." (PMID 22768033, 2012). "Nicorandil suppresses the inflammatory cytokines IL-1β, IL-1, IL-6, IL-10, IL-18, IL-19 and TNF-α in acute coronary syndrome patients." (PMID 34595611, 2023). "Acute coronary syndrome patients with CCs in culprit lesions had a higher expression of NLRP3, IL-1β, and IL-18, and had more vulnerable plaque characteristics than patients without CCs." (PMID 36386333, 2022). "As far as inflammasome activation occurs in two phases, it is presumed that in acute coronary syndromes ischemic injury is responsible for priming the NLRP3 and pro-IL-1β by locally released DAMPs." (PMID 35055149, 2022). "Colchicine, a potent non-specific anti-inflammatory drug, also lowers NLRP3 expression and serum levels of IL-1β and IL18 in patients with acute coronary syndromes." (PMID 35055149, 2022). "The monoclonal antibody canakinumab, an anti-IL-1β agent, demonstrated significant reduction of CRP and improved CV outcome in patients with acute coronary syndromes." (PMID 35055149, 2022). "Platelets, vital for the pathogenesis of acute coronary syndromes (ACS), are both the objective of IL-1b and its abundant source." (PMID 33801199, 2021). "In the present study, we explored the relationship between serum and EAT levels of IL-1β and IL-1 receptor antagonist (IL-1ra) in patients with chronic coronary syndrome (CCS) and recent acute coronary syndrome (ACS)." (PMID 32116755, 2020).
bone cancer (29 papers, 2010 to 2025). A primary or metastatic malignant neoplasm affecting the bone or articular cartilage. "In addition, a previous study suggests that IL-33 plays an essential role in bone cancer pain, and its actions might be associated with inducing spinal upregulation of IL-1β and TNF-α." (PMID 29329586, 2018). "In the process of bone cancer pain, spinal microglia showed increased M1 polarization, decreased M2 polarization, increased IL-1β expression and decreased IL-10 expression." (PMID 39679363, 2024). "A similar outcome was observed in animal studies in which LNCaP cells harvested from osseous tumors of mice treated with enzalutamide robustly upregulated IL1β." (PMID 36561929, 2022). "It was demonstrated that intrathecal injection of agents activating CB2 inhibits glial cells and downregulates the expression of IL-1β and IL-6, reducing bone cancer pain." (PMID 34576321, 2021). "During tumor growth and development of bone cancer pain, certain proinflammatory cytokines such as TNF-α and IL-1β are activated and released from the astrocytes and microglial cells and contribute to bone cancer pain." (PMID 26989332, 2016). "Our results indicate that XAT decoction can effectively alleviate bone cancer pain, suppress morphine-induced adverse actions, reduce the proinflammatory cytokines IL-1β and TNF-α, and increase the endogenous anti-inflammatory cytokine IL-10." (PMID 26617438, 2015). "In support of our findings, previous studies also reported selective localization of increased IL-1β in spinal astrocytes in bone cancer pain model and Complete Freunds adjuvant-induced inflammatory pain model." (PMID 21969850, 2011). "Interleukin, IL1β released from glial cells is reported to facilitate bone cancer pain by enhancing phosphorylation of NMDA receptor NR-1 subunit." (PMID 20602757, 2010). "A previous study demonstrated that IL-1β was upregulated in a bone cancer pain rat model and that intrathecal IL-1ra produced an anti-pain effect in such a model." (PMID 20089147, 2010). "Similar to TNF-α, IL-1β is expressed in both microglia and astrocytes and is upregulated in astrocytes in various chronic pain conditions, including inflammatory pain, neuropathic pain, and bone cancer pain." (PMID 40349773, 2025). "This study found that intrathecal injection of hPPE-modified hBM-MSCs could effectively relieve bone cancer pain in rats by inhibiting the expression of pro-inflammatory cytokines, including IL-1β and IL-6." (PMID 39020426, 2024). "Then, microglial activation with an increase in inflammatory cytokines in bone cancer pain rats was imitated using an LPS treatment in vitro; and miR-155-5p knockdown alleviated the augment of Tnf, Il1b, and Il6, which was possibly achieved by suppressing Sgk3 in vitro." (PMID 36143385, 2022). "In addition, the inhibition of the NF-κB signaling pathway and its downstream inflammatory factor IL-1β suppressed oxidative stress and inflammation in the developmental process of bone cancer pain." (PMID 34440578, 2021). "Moreover, some research suggests that EA may decrease the activity of spinal glial cells and astrocytic IL-1β expression in a rat model of bone cancer pain." (PMID 40064496, 2025). "The results showed that intrathecal injection of miR-9-5p modified BM-MSCs could reduce the expression of REST and increase the expression of MOR, inhibit the release of inflammatory factors TNF-α, IL-6, and IL-1β in the spinal cord dorsal horn of mice, and relieve bone cancer pain." (PMID 39020426, 2024). "Thus, the blockade of spinal HMGB1 could attenuate bone cancer pain and downregulate the expression of IL-1β in a dose-dependent manner." (PMID 34638667, 2021). "Studies have demonstrated that astrocytes and microglial cells, which act as parts of the innate immune system, become active in the status of bone cancer and release various substances, including the proinflammatory cytokines IL-1β and TNF-α, which could evoke hyperalgesia and allodynia." (PMID 26617438, 2015).
bone cancer (continued). "In bone cancer, OT alleviates bone cancer pain by inhibiting the upregulation of TLR4, TNFα, and IL-1β in the spinal cord." (PMID 39290327, 2024). "Several pro-inflammatory cytokines (IL-1β, TNFα, IL-6, and TGFβ) and inflammatory mediators (CGRP) are increased in the DRG in response to bone cancer and fracture." (PMID 27199772, 2016). "Among array-identified genes, three (i.e., FABP4, IL-1β, and HMOX-1) were also significantly induced in experimental PC3 bone tumors from HFD mice as compared to LFD mice." (PMID 24240026, 2013). "In bone cancer pain, short-term exposure of cancer-related fibroblasts, MSCs, and osteoblasts to pH 6.8 can promote the expression of inflammatory and nociceptive mediators (NGF, BDNF, IL-6, IL-8, IL-1b, and CCL5), leading to nociceptor sensitization and hyperalgesia." (PMID 39679363, 2024).
head and neck squamous cell carcinoma (29 papers, 2011 to 2025). A squamous cell carcinoma that arises from any of the following anatomic sites: lip and oral cavity, nasal cavity, paranasal sinuses, pharynx, larynx, and salivary glands. "Inhibiting IL-1β or NLRP3 inflammasome (a key component for IL-1β maturation) reduces MDSCs and enhances antitumor immunity in head and neck squamous cell carcinoma models." (PMID 38008741, 2023). "IL-1β elicited ICAM1 expression by modulating intracellular ROS levels in head and neck squamous cell carcinoma, thereby fostering drug resistance." (PMID 37865637, 2023). "This is supported by studies showing that activation of NLRP3 inflammasome/IL-1β pathway promotes head and neck squamous cell carcinoma tumorigenesis while inactivation of this pathway delayed tumor growth." (PMID 34357109, 2021). "For instance, the NLRP3 inflammasome/IL-1β pathway enhanced immunosuppressive cell accumulation to facilitate the tumorigenesis of head and neck squamous cell carcinoma (HNSCC)." (PMID 31492049, 2019). "In a head and neck squamous cell carcinoma (HNSCC) mouse model inflammasome activation and thereby IL-1β upregulation was shown to cause an insufficient anti-tumor reactivity via the immunosuppressive network of MDSC, TAM and Treg." (PMID 30042333, 2018). "Moreover, the enrichment of Candida albicans has also been correlated with an increase in the inflammatory cytokines interleukin (IL)-1β and IL-8 in the saliva of patients with head and neck squamous cell carcinoma (HNSCC)." (PMID 35910636, 2022). "Increased IL-1β production is also observed in head and neck squamous cell carcinoma (HNSCC) patients." (PMID 36742298, 2023). "Indeed, IL-1β could initiate M2 macrophage polarization, which also contributes to tumor growth in head and neck squamous cell carcinoma." (PMID 34150748, 2021). "Moreover, SPP1+ macrophages augment the secretion of TNF-α and IL-1β via the NF-κB pathway, further supporting proliferation in head and neck squamous cell carcinoma (HNSCC)." (PMID 41417432, 2025). "For example, in pancreatic ductal adenocarcinoma (PDA) and head and neck squamous cell carcinoma (HNSCC), inflammasomes of tumor-associated macrophages activate caspase-1 and mediate the cleavage of GSDMD and the release of mature IL1β, resulting in the suppression of CD8+ T cells." (PMID 36199426, 2022). "In human head and neck squamous cell carcinoma (HNSCC), NLRP3, ASC, CASP1, IL1B and IL18 gene expression is increased as compared to oral mucosa." (PMID 33261061, 2020).
lymphoma (29 papers, 2012 to 2025). A malignant (clonal) proliferation of B- lymphocytes or T- lymphocytes which involves the lymph nodes, bone marrow and/or extranodal sites. "The observed increase in IL-1β across lymphomas underscores its role in promoting a pro-inflammatory microenvironment that supports coagulation activation." (PMID 40076681, 2025). "As a platelet activation marker, P-selectin was generally increased in lymphomas with thrombosis, while pro-inflammatory cytokine IL-1β was largely increased in DLBCL, FL, and HL." (PMID 40076681, 2025). "In line with this, an important role of IL-1β has been identified in inflammation-induced and AhR-dependent tumor promotion of lymphoma in mice." (PMID 37696458, 2023). "In a subsequent study, the same group of authors synthesized ten new (+)-UA imidazolium salts, which were evaluated for the in vitro anti-inflammatory potential of TNF-α and IL-1β on the LPS-stimulated human lymphoma U937 cell line." (PMID 37109575, 2023). "The important role of IL-1β has also been demonstrated in AhR-mediated (TCDD-induced) development of lymphoma." (PMID 37696458, 2023). "Remarkably, in vivo administration of the NLRP3 inhibitor, MCC950, repressed lymphoma expansion and reduced the concentrations of IL-1β and IL-18, consequently downregulating PD-L1." (PMID 35897704, 2022). "This complemented our results which reflected that IL-1β was highly elevated in lymphoma pre-treatment patient but regretted in the post treatment levels compared with pre-treatment and control levels value." (PMID 30814315, 2019). "Although TNF-α has anti-apoptotic signals via the nuclear transcription factor (NF)-κB pathway, it influences lymphoma development through pro-inflammatory cytokines such as IL-1β, IL-6, and IL-8." (PMID 30814315, 2019). "As for another NLRP3 effector molecule, though plasma IL-1β level in newly-diagnosed lymphoma patients was significantly higher than in controls (p = 0.0031), no significant decrease was found after chemotherapy remission (p = 0.1015)." (PMID 29312552, 2017). "Among the 11 analyzed cytokines, IL-8, IL-4, and IL-1β levels were significantly different from control depending on the lymphoma subtype using one-way analysis of variance among control and lymphoma subtypes (P = 6.69E−05, 7.46E−05, and 0.0043, respectively)." (PMID 26674732, 2015). "In a mouse model of intraperitoneal injection of necrotic lymphoma cells or acetaminophen-induced liver injury, neutrophil recruitment to the peritoneal cavity or liver was mediated by IL-1α alone or both IL-1α and IL-1β, respectively." (PMID 23209417, 2012). "Anti-inflammatory agents targeting IL-1β or TNF-α, along with anticoagulants, may represent promising avenues for reducing thrombosis risk in lymphoma patients." (PMID 40076681, 2025). "Moreover, MyD88-L265P-driven lymphomas enriched for PU.1 and C/EBPβ gene sets, and exhibited high-level expression of the respective TF and their target genes, such as Csf1r and Il1b." (PMID 40159497, 2025). "In lymphomas, IL-1α may have anti-tumoral properties, whereas IL-1β has been shown to be expressed in HL cells from areas of tissue with active fibrosis, and the receptor IL-1R2 may contribute to local and systemic modulation in the disease." (PMID 36555171, 2022). "To test whether BAFF activated through proteolytic processing of pro-caspase-1 and pro-IL-1β, we treated two lymphoma cell lines and primary B cells with different concentrations of BAFF." (PMID 33004801, 2020). "In addition, NLRP3 inflammasome increases IL-18 and IL-1β production, thereby promoting tumor cell proliferation and inhibiting apoptosis during lymphoma development." (PMID 32063899, 2019). "Contrary to MCP-1 and anti-inflammatory TGF-β, we have increased IL-1β (5.2-fold), TF, and P-selectin levels (2-fold) in joined DLBCL and DLBCL-like lymphomas with an aggressive form of development." (PMID 40076681, 2025).